EGFR (epidermal growth factor receptor)
Diseases named in the same sentence as EGFR in open-access papers (continued):
Sharing a sentence is not in itself a finding about the gene and the disease.
tumor (continued). "Directing recombinant single-chain TRAIL molecules to tumor-specific surface antigens using a diabody-based forced dimerization strategy is not limited to the EGFR and together with appropriate apoptosis sensitizing agents may be a powerful approach to efficiently kill a broad range of cancer cells." (PMID 25198428, 2014). "Taken together, these data suggest that EGFR activation induces a cascade of events leading to an increase of the ability of MSCs to both release factors favouring tumor progression and respond to signals involved in the cross-talk with cancer cells within the tumor microenvironment." (PMID 25344915, 2014). "In conclusion, our results indicate that PI4KIIα knockdown reduces EGFR protein level in a degradation-dependent pathway, and the dual inhibition of EGFR protein level by PI4KIIα RNAi and EGFR activity by its specific small molecular inhibitors exerts superior outcomes for tumor therapy." (PMID 24801752, 2014). "While EGFR overexpression is thought to be an early event in cancer development, the downregulation of E-cadherin may occur at later stages of cancer progression, thereby leading to tumor invasion and metastasis." (PMID 24722213, 2014). "Thus, TGF-β might at least play a harmful role in antitumor T cell responses against tumor treated with EGFR inhibitor." (PMID 25240937, 2014). "Indeed, incomplete targeting of EGFR isoforms could simply drive tumor evolution toward a cellular population expressing an untargeted (resistant) variant." (PMID 24292886, 2014). "However, some studies showed emergence of T790M in acquired resistant tumor tissues was associated with superior prognosis after EGFR-TKI compared with those without T790M." (PMID 25405807, 2014). "Claudin-4 negative to positive conversion in the metastases was significantly associated with tumor size (p = 0.015; 11/14 versus 31/72), whereas negative to positive conversion of EGFR was associated with negative PR status (p = 0.046; 8/8 versus 46/75) and high MAI (p = 0.047; 8/8 versus 47/75)." (PMID 25417118, 2014). "For some of the NSCLC patients, especially those with metastatic cancer, the primary tumor specimen may not be available; therefore EGFR mutations in metastases are often analyzed." (PMID 24398248, 2014). "In addition to clonal selection of resistant cells in the initial tumor, cells carrying L747S may predominate following EGFR-TKI therapy." (PMID 24396447, 2014). "Another explanation could be that some tumours contain several clones of which only some contain mutations in the EGFR gene and that the biopsy was taken in a clone without EGFR mutation." (PMID 24773774, 2014). "In conclusion, our data demonstrate that EGFR activation leads to a significant change in the expression of a wide array of genes coding for secreted proteins that can significantly enhance tumor progression by acting on several mechanisms within the tumor microenvironment." (PMID 25344915, 2014). "AG1478, an EGFR inhibitor, may inhibit tumor formation and progress in mouse OSCC models." (PMID 25051199, 2014). "In this review, we will appraise the current knowledge on primary and acquired resistance to anti-EGFR moAbs in mCRC, from initial mechanistic exploration to clinical applications, and will highlight emerging lines of investigation aimed at improving response and delay relapse in this tumor setting." (PMID 24811491, 2014). "Furthermore, the time-dependent changes in the sensitivity of tumor cells may be related to the EGFR signaling pathway." (PMID 25000529, 2014). "However, a separate study indicates that Neu1 salidase enhances EGFR signaling and thus could be tumor promoting." (PMID 25184537, 2014). "However, the presence and severity of cutaneous toxicity has shown to have positive correlation with patient survival and could be a surrogate marker for tumor response, especially for the epidermal growth factor receptor inhibitors (EGFRI)." (PMID 24723942, 2014).
tumor (continued). "Therefore, combined inhibition of PI4KIIα and EGFR showed tripled anti-tumor effect." (PMID 24801752, 2014). "Our results suggest that the EGFR mutation status assessed prior to chemotherapy may not accurately reflect the mutation status post-chemotherapy, which supports a “real-time” tumor profiling in the personalized therapy of NSCLC." (PMID 23520442, 2013). "Although the correlation between EGFR mutation and ERCC1 has been unclear, it can be postulated that an impaired capacity for DNA repair and synthesis may be correlated with increased genome instability and tumor mutations." (PMID 23940741, 2013). "However, IgA EGFR may activate complement via the lectin or the alternative pathway, which could lead to deposition of complement fragments, such as iC3b, on tumour cells." (PMID 23918228, 2013). "No cases of concurrent presence of KRAS and EGFR mutations were observed in the same tumor sample." (PMID 23817662, 2013). "The strongest anti-tumor effects were exhibited by the combination of high dose crizotinib and a new generation EGFR-TKI, which reduced tumor proliferation and increased tumor apoptosis in vivo, indicating that complete dual blockade of mutant EGFR and Met may overcome resistance to EGFR-TKIs." (PMID 24386407, 2013). "Furthermore, these results indicate that the disseminating tumor cells at the invasive marginal regions of tumors may undergo EMT, when loss of E-cadherin induces ERK activation through deregulated EGFR activation, eventually promoting invasion." (PMID 24318272, 2013). "In addition, exogenous factors from the tumor microenvironment, including hepatocyte growth factor and interleukin-6, may also play a role in primary EGFR TKI resistance." (PMID 24376677, 2013). "Hence, the discrepancy between our findings and those reported in the literature may reflect major differences existing between normal and tumour epithelial cells in EGFR turnover." (PMID 23527233, 2013). "Furthermore, immunostaining was weakly positive for phosphatase and tensin homolog (PTEN) in tumor cells and strongly positive in endothelial cells; weakly focally positive for epidermal growth factor receptor (EGFR); and positive for Ki67 in approximately 15–20% of cell nuclei." (PMID 24222871, 2013). "Notably, we could verify the 4-6-fold amplification of EGFR locus in SK01600 primary tumor, encompassing a 5 MB segment." (PMID 23441165, 2013). "Therefore, EGFR-TK is an attractive molecular target for tumor diagnosis." (PMID 23494210, 2013). "Moreover, targeting of hypoxic tumor cells with the α-emitter 213Bi could possibly be achieved independently of EGFR targeting." (PMID 23724085, 2013). "Thus, if the amount of mutated tumor cells in the sample is below that limit or some other uncommon EGFR mutation was present, the test would be false negative." (PMID 24205040, 2013). "Notably, treatments with pharmacologic inhibitors of EGFR or mTor are cytostatic at best in a subset of patients, indicating that other, unidentified factors or compensatory signals affect the survival and growth of tumor cells." (PMID 23459592, 2013). "Any EGFR WT result should be carefully assessed as it might reflect sampling bias, particularly when the analysis was performed using DNA isolated from a small number of tumor cells." (PMID 23817662, 2013). "However, both EGFR over-activation and hypoxia typically co-exist within the tumour microenvironment and both may impact upon the differential modulation of angiogenic responses induced by either stimulus." (PMID 24180698, 2013). "In GC, EGFR positivity is considered to be a negative prognostic factor in GC, and biomarker analysis shows that EGFR positivity is associated with poor patient outcomes after curative resection of tumor tissue." (PMID 24454509, 2013).
tumor (continued). "Among them, EGFR(7p11.2), TWIST1(7p21.2), RAC1(7p22), MTDH(8q22.1), CCNE2(8q22.1), TNFRSF11B(8q24) and GRB2(17q25) might be good candidates, as they are reportedly associated with invasiveness and metastasis of tumor cells." (PMID 23457519, 2013). "In this study it was hypothesized that, due to its smaller size, fluorescently labeled anti-EGFR Affibody protein (∼7 kDa) would provide a more clear delineation of the tumor margin than would fluorescently labeled cetuximab, a full antibody (∼150 kDa) to the epidermal growth factor receptor (EGFR)." (PMID 23593208, 2013). "By blocking EGFR activation and its downstream signaling, such as the PI3K-AKT and RAS-MAPK pathways, these anti-EGFR agents enhance the cytotoxic effect of ionizing radiation by inducing cell cycle arrest and apoptosis and inhibiting cell proliferation, metastasis and tumor angiogenesis." (PMID 23976954, 2013). "Together, these data suggest that while stabilization of activated EGFR by AnxA6 may be important in the dissemination of invasive tumor cells, EGFR activity is dispensable in the enhanced proliferation of cells that either lack, or express low levels of AnxA6." (PMID 24354805, 2013). "Furthermore, EGFR signaling is well-known to enhance tumor cell motility." (PMID 23869217, 2013). "The purpose of this study was to evaluate whether early changes in 3′-deoxy-3′-3H-fluorothymidine (3H-FLT) uptake can reflect the antiproliferative effect of gefitinib in a human tumor xenograft, in comparison with the histopathological markers, Ki-67 and phosphorylated EGFR (phospho-EGFR)." (PMID 24191959, 2013). "Hence, EGFR appears to be a key molecule for uPAR-mediated tumour progression." (PMID 25937961, 2013). "Hence, IGF-1R (like EGFR) may play a role in maintaining intracellular glucose levels in tumor cells in a kinase-independent manner." (PMID 23531874, 2013). "Repopulation depends on the activation of signaling pathways that stimulate the proliferation of tumor cells and many molecular-targeted agents have been developed that inhibit these pathways, such as gefitinib which targets epidermal growth factor receptor (EGFR) signaling." (PMID 23762282, 2013). "If the tumor is negative, it will be tested for EGFR mutations and EML4-ALK translocation." (PMID 23341890, 2013). "In our present work, we find that, beyond its EGFR tyrokinase inhibitory effect, gefitinib also has immunomodulatory effect in gefitinib-resistance cell lines, which can enhance immune recognization of tumor cells by NK cells and attenuate the inhibitory effect of tumor cells on NK cells." (PMID 23937717, 2013). "However, we screened a larger cohort of tumor samples, and we focused our attention on EGFR mutation-negative samples that were 22 in our training set (16 NSCLC and 6 CRC cases), whereas they were only 5 in the previous report." (PMID 24364033, 2013). "Thus, one can speculate if the level of resistance to EGFR inhibitors would follow the expression levels of mutant KRAS transcripts in the different tumor compartments." (PMID 24280411, 2013). "Moreover, activation of EGFR was involved in LPS-activated tumor cell proliferation." (PMID 22923191, 2013). "Using a clinically relevant human GBM xenograft model, we show that tumor cells with EGFR gene amplification and activation diffusely infiltrate normal brain tissue independent of angiogenesis and that transient inhibition of EGFR activity by cetuximab inhibits the invasive tumor growth." (PMID 23429996, 2013). "However, 20–40% of NSCLC patients do not experience tumor reduction following EGFR TKI administration despite the presence of EGFR mutations in their tumors." (PMID 24376677, 2013). "However, anti-EGFR antibody therapy exerts early tumor shrinkage and thus is hypothesized to represent a suitable choice for the treatment of patients with advanced mCRC and a poor PS." (PMID 24137455, 2013).
tumor (continued). "However, a phase II study of single agent dasatinib in advanced NSCLC showed that neither activation of SFK nor EGFR and Kras mutations in tumor tissue predicted response to dasatinib." (PMID 23721490, 2013). "The prognosis of patients in whom the tumor tissue consists of a mixture of mutant EGFR cells and wild-type EGFR cells has been reported to be inferior to that of patients with tumors consisting of only mutant EGFR cells, and intratumor heterogeneity has also been investigated." (PMID 23879483, 2013). "A targeted peptide vaccine against EGFRvIII, a mutated form of the EGFR, entered a phase I clinical trial, the Vaccine for Intra-Cranial Tumors I (VICTORI), and has continued to the phase II study, A Complementary Trial of an Immunotherapy Against Tumor Specific EGFRvIII (ACTIVATE)." (PMID 23762610, 2013). "In addition, these spheroids harbored increased expression of genes that are activated if cooperation between the Hedgehog and EGFR pathways occurs, and depend on these Hedgehog-EGFR cooperation responsive genes for in vitro spheroid formation and in vivo tumor growth." (PMID 24213498, 2012). "However, the threshold mutation load within a K-ras mutant tumour specimen is not well defined; beyond which there is definite futility of the use of anti-EGFR antibodies in patients." (PMID 22666589, 2012). "Interestingly, when the relationship has been studied, the rash has been uniformly correlated with better clinical outcomes (objective tumor response and patient survival) both when the anti-EGFR agents are used as single agents or in combination with chemotherapy." (PMID 22997576, 2012). "Moreover, EGFR overexpression was associated with a higher nuclear grade, larger tumor size and shorter patient's survival, while there was no connection with pathological stage." (PMID 22475688, 2012). "However, the EGFR amplification is less specific in secondary GB, though it has been shown that EGFR overexpression is a relatively late event in the dedifferentiation of glia-tumor cells." (PMID 22264301, 2012). "These include: increased expression of growth factor receptors (e.g., EGFR), elevated glucose metabolism and up-regulated glucose transporters (e.g., Glut-1) and an increased tissue proteolysis by the tumor, through upregulation of proteolytic enzymes such as MMP-2, -9 and cathepsin B and D." (PMID 22348134, 2012). "The EGFR/PDGFR-c-Src-Notch may be a key pathway influencing the malignant behavior of tumor cells." (PMID 22479394, 2012). "The rationale for targeting the EGFR pathway comes from the following observations: there is a high frequency of EGFR overexpression in HCC, and this overexpression has been associated with late-stage disease, increased cell proliferation and degree of tumor differentiation." (PMID 22470194, 2012). "The roles of the different EGFR isoforms are largely unknown in tumor pathology." (PMID 22623992, 2012). "Since the receptor for these ligands, EGFR, plays a critical role in cancer cell migration and tumor metastasis, we investigated whether EGFR signaling in the mesenchymal progenitors mediates the chemotactic effects of conditioned media from PTH-treated osteoblasts." (PMID 23300521, 2012). "Besides proper definition of the target population and tumor characteristics, it is important to reflect distinct information of immunohistochemical EGFR expression like intensity of staining, staining pattern (focal or homogenous), content of tumor cells and choice of primary antibodies." (PMID 23153332, 2012).
tumor (continued). "The variation in mutations between primary tumours and metastases may occur, and consequently, mutations in the primary tumour may not be sufficient to predict the response of metastases to EGFR-targeted monoclonal antibodies." (PMID 23226727, 2012). "Therefore, relative Sox2 expression and functions within the tumor-CSCs may be a major determinant in EGFR-targeted therapy against NSCLCs." (PMID 23009336, 2012). "Similarly, ErbB2-driven tumor cells are EGFR-dependent and also display HGF-mediated rescue." (PMID 23028720, 2012). "Therefore, the aim of this study was to assess whether EGFR expression predicts tumor staging and survival in EA patients treated with a standardized surgical technique." (PMID 22792097, 2012). "Furthermore, lesions with expressed EGFR showed poorer tumor differentiation." (PMID 22792097, 2012). "As such, anti-EGFR drugs (Section 7.1.2) are not recommended in KRAS-mutated tumours." (PMID 22997602, 2012). "EGFR expression is not related to age, smoking, gender, pathogenic stage or tumor status." (PMID 23133538, 2012). "In the absence of EGFR mutations in tumor cells, we hypothesized that receptor stimulation might depend on the production of high EGF levels in the tumor microenvironment." (PMID 23056514, 2012). "However, the tumor response rate increased by anti-EGFR MAbs was only 10%-20%, whether it be used as the 1st- or 2nd-line treatment." (PMID 22897982, 2012). "However, the response is heterogeneous with respect to the different expressions of EGFr in the patient population and also to the sub-sites, as accelerated repopulation of clonogenic tumour cells and locoregional control could arise." (PMID 22920680, 2012). "Our knowledge on the role of EGFR in the cell biology has been further expanded with the emergence, in recent years, of new experimental data demonstrating an interplay between oncogene signaling pathways, tumor metabolic re-programming and cancer-related inflammation." (PMID 24212794, 2011). "Moreover, patients presenting an EGFR promoter methylated tumour experienced in fact a worse clinical outcome thus confirming our hypothesis of a role for EGFR promoter methylation in determining the efficacy of anti-EGFR-targeted monoclonal antibodies." (PMID 21559018, 2011). "In conclusion, our finding suggested that, when body fluids were used for EGFR mutation analysis, positive result is consistently a good indicator for TKIs therapy, and the predictive effect was no less than that of tumor tissue, no matter what method was employed." (PMID 22142557, 2011). "Similarly, growth inhibition induced by gefitinib or erlotinib in A549 cells was enhanced after autophagy was inhibited by the knockdown of ATG5 or ATG7, two essential components for the formation of autophagosome, confirming that autophagy protected tumor cells from EGFR-TKIs induced cell death." (PMID 21655094, 2011). "Similarly, the EGFR and its constitutively activated variant EGFRvIII were shown to bind to and sequester the proapoptotic Bcl-2 family member PUMA in the cytoplasm leading to tumour drug resistance." (PMID 22035226, 2011). "Interestingly, we observed significantly lower pEGFR immunoexpression in HPV-positive than HPV-negative tumours (p = 0.0143) which contradicts the cell culture model hypotheses and suggests a greater role of EGFR in HPV independent penile carcinogenesis." (PMID 21407808, 2011). "We did not examine the upstream defects responsible for the activation of Akt; however, we did find that EGFR tyrosine phosphorylation was significantly elevated in 6 of these 12 tumours, suggesting that changes in EGFR activity might have been responsible (data not shown)." (PMID 21505451, 2011). "The decreased EGFR expression in the perimeter of tumors established from normoxic cells relative to the core may be because the core of the tumor is more starved for growth factor activation, and hence increases EGFR in an attempt to be more susceptible to growth factors." (PMID 21320311, 2011).